STAT3 (signal transducer and activator of transcription 3)
Diseases named in the same sentence as STAT3 in open-access papers (continued):
Sharing a sentence is not in itself a finding about the gene and the disease.
lung carcinoma (continued). "Additionally, we found that BDNF expression was under the control of STAT3 and was decreased upon the inhibition of STAT3 activity by Stattic in A549 and H1299 cells, thus establishing STAT3 as a critical regulator of BDNF in lung cancer cells." (PMID 27456333, 2016). "In addition, PD-L1 expression of the PD-L1-amplified lung cancer cell line, HCC4006, is shown to be reduced by JAK2-specific and STAT3-specific inhibitors." (PMID 27050074, 2016). "The first JAK inhibitor approved by FDA for haematologic disease is ruxolitinib, and the use of ruxolitinib in STAT3 activated lung cancer cell line does not prove activity." (PMID 27433281, 2016). "In addition, the Notch and JAK/STAT3 signaling pathways were inhibited by Notch-1 siRNA and JSI-124, respectively, to determine the roles of these pathways in lung cancer cells." (PMID 27185268, 2016). "Our findings suggested that leptin knockdown could become a new approach for the prevention of lung cancer progression, which is likely to be mediated at least partially by inactivation of the Notch and JAK/STAT3 signaling pathways." (PMID 27185268, 2016). "Our data indicated that digoxin suppresses FAK-Src, paxillin, PI3K/AKT, MEK/ERK, STAT3 and p130Cas-JNK signaling pathways in various EGFR-containing lung cancer cells, suggesting that digoxin inhibits cancer cell invasion by decreasing Src activation and the activation of related signaling pathways." (PMID 25955608, 2015). "Similarly, STAT3 has been reported to be activated upstream of SOX2 in breast and lung cancer stem cells." (PMID 26370982, 2015). "To demonstrate the critical role of the TNF-α/NF-κB/cyclinD1 and IL-6/STAT3/cyclinD1 pathways in the malignant transformation of 16HBE cells, we first detected the expression levels of TNF-α, IL-6, NF-κB, STAT3, and cyclinD1 in lung cancer tissues." (PMID 25823926, 2015). "Higher level of interleukin-6 (IL-6) existed in lung cancer patients and mutant EGFR and TGFβ signal requires the upregulation of IL-6 through the gp130/JAK pathway to overactive STAT3, an oncogenic protein which has been considered as a potential target for cancer therapy." (PMID 26166037, 2015). "Our data demonstrated that miR-197 regulates lung cancer drug resistance and tumor progression by directly targeting the cyclin-dependent kinase CKS1B as well as by indirectly targeting the transcription factor STAT3." (PMID 25597412, 2015). "Although various oncogenic targets have been described to account for the potent anticancer activities of BSN, our study is the first one to explore the effects of BSN both on STAT3 signaling pathway and on the negative regulators of STAT3 signaling (PIAS-3 and SOCS-3) in human lung carcinoma." (PMID 25788267, 2015). "BP-1-102, an analog of S3I-201, inhibits STAT3 through the same mechanism by binding to the SH2 domain and selectively suppresses malignant cell growth, survival, transformation, migration, and invasion in human breast and lung cancer cells." (PMID 24743778, 2014). "In lung cancers JAK1 and JAK2 induce oncogenic signaling through STAT3." (PMID 24833526, 2014). "In this study, we have demonstrated that in human lung cancer cells, gefitinib treatment induces, rather than suppresses STAT3 activation as extrapolated from traditional EGFR signaling orthodox." (PMID 24280348, 2013). "Accordingly, combinational targeting of STAT3, Akt and EGFR may prevent or reverse drug resistance of EGFR TKI-based therapy in the lung cancers." (PMID 24280348, 2013). "Overall, our findings support that STAT1, but not STAT3, plays a primary role in inhibition of pro-angiogenic factor production in human lung cancer by IL-27 treatment." (PMID 24274066, 2013). "Together, these results suggested that MET, EGFR, HER2, and HER3 activate AKT and ERK signalling pathways and promote cell proliferation and survival in lung cancer cells with MET amplification, whereas MET, HER2, and RET activate the STAT3 signalling pathway and promote cell migration." (PMID 21847121, 2011).
lung carcinoma (continued). "Furthermore, recent study showed that the novel Stat3 target gene Bcl-XL inhibitor, ABT-737, greatly enhanced the activities of paclitaxel in lung cancer cells." (PMID 20459702, 2010). "Since cancer is now viewed not only as being the consequence of uncontrolled proliferation, but also as the result of an altered balance between cell proliferation and rate of apoptosis, we examined the effects of STAT3 decoy ODN on cell proliferation and apoptosis of lung cancer cells." (PMID 17683579, 2007). "In conclusion, our study establishes DCAF12 as a primary regulator of lung cancer metastasis through a dual mechanism: stabilizing the TRiC/CCT complex via non‐degradative ubiquitination to maintain cytoskeletal dynamics, and concurrently activating the YAP, STAT3, and mTOR pathways." (PMID 41047465, 2026). "Additionally, GA suppressed the proliferation and migration of human lung cancer cells and could enhance the antitumor properties of DDP via regulating the Janus kinase/STAT3 pathway and related apoptotic molecules." (PMID 40486873, 2025). "Therefore, the development of new STAT3-targeted drugs may realize the dual targeting effect on CAF and lung cancer cells, and play the role of EGFR-TKI resistance reversal." (PMID 40703348, 2025). "In lung cancer, the N-myristoylation of enhancer of zeste homolog 2 (EZH2) facilitates the formation of LLPS droplets that concentrate the substrate signal transducer and transcription 3 (STAT3) activator, thereby increasing STAT3 signaling and driving cell proliferation." (PMID 40335986, 2025). "Notably, JAK2 activation modulates STAT3 phosphorylation, it has been shown that nicotine interacts with cell surface α5-nAChR to activate various signaling pathways, including the JAK2/STAT3 pathway, thereby affecting lung cancer progression." (PMID 40143965, 2025). "Similarly, neither mTOR nor STAT3 alone served as a key determinant in lung cancer patient prognosis." (PMID 38886756, 2024). "It has also been found to reduce JAK2/STAT3 signaling and induce autophagy through the production of ROS in SKOV3/DDP ovarian tumor cells resistant to cisplatin 29, as well as suppressing the growth of lung cancer by blocking β-catenin induction of the epithelial-mesenchymal transition." (PMID 39513117, 2024). "Furthermore, only the expression of PPAR-γ and Arg1 but not other key transcription factors such as STAT1, STAT3 and C/EBPβ was dramatically reduced in Ffar2−/− MDSCs and urethane-induced lung cancer tissues." (PMID 38402237, 2024). "KRAS-mutant lung cancer bone metastasis tissue exhibited higher p-STAT3Tyr705 levels at day 28 after intracardiac injection than at day 7, suggesting that activation of IL6/JAK/STAT3 pathway may be involved in the enhanced resistance to HOXC10 inhibition." (PMID 39191757, 2024). "Further, niclosamide was reported to retrieve the sensitivity to radiation of triple-negative breast cancer (TNBC) cell lines via suppression of STAT3 and Bcl-2 and production of ROS, and was also able to overcome radioresistance in human lung cancer cells and in lung cancer xenografts." (PMID 36675241, 2023). "One study confirmed that after treating A549, H358, H460 and LLC cells with hypoxic BMSC-EVs, hypoxic BMSC-EVs could transfer miR-193a-3p, miR-210-3p and microRNA-5100 into lung cancer cells and activate STAT3-induced EMT, thereby promoting metastasis of lung cancer cells." (PMID 35860555, 2022). "In conclusion, the findings of this study verify that senescent fibroblasts potentially promote lung cancer metastasis to gain a CAF phenotype, and provide evidence that intracellular ROS accumulation in senescent fibroblasts may activate the Stat3 pathway during CAF phenotype activation." (PMID 36140747, 2022). "Here, we review the cell type-specific functions of STAT3 in the pathogenesis and progression of KM-LUAD that could serve as a new target for personalized preventive and therapeutic intervention for this intractable form of lung cancer." (PMID 35406557, 2022).
lung carcinoma (continued). "The Rab37/IL-6/STAT3/PD-1 axis in immune cell models prompted us to determine whether concurrent blockade of IL-6 and CTLA-4 in vivo would provide a rational treatment to circumvent current PD-1-targeted immune-modulatory therapy for lung cancer." (PMID 34093869, 2021). "The current study demonstrated the LC-C sensitized ionizing radiation-resistant lung cancer cells to radiation both in vitro and in vivo, and the radiosensitization effect was attributed to the up-regulation of ERRFI1 and the down-regulation of EGFR/STAT3 pathway." (PMID 33869036, 2021). "However, the anticancer effects of SB in EGFR TKI-resistant lung cancer cells, and the role of signal transducer and activator of transcription 3 (STAT3) in the SB-induced apoptosis have not been elucidated yet." (PMID 34068421, 2021). "We demonstrated that TIM‐4 overexpression could lead to STAT3 activation in lung cancer cells, while TIM‐4 did not induce phosphorylation of NF‐κB." (PMID 32020709, 2020). "Although the statistical analysis showed that there was no significance for STAT3 staining in lung cancer and prostate cancer, which might be owing to the small sample size, the abnormal expression of STAT3 in cancer was obvious." (PMID 32486001, 2020). "Importantly, when we silenced STAT3 and treated cells with both FZKA and Gefitinib, cell apoptosis were much more induced compared to control group, indicating the critical role of STAT3 in the induction of lung cancer cell apoptosis." (PMID 32489321, 2020). "The expression of PD-L1 on tumor cells might be induced by the secretion of IFNγ via Janus kinase/signal transducer and activator of transcription 3 (JAK/STAT3) and the phosphatidylinositol 3-kinase (PI3K)/protein kinase B (Akt) signaling pathways, which has been shown in lung cancer." (PMID 31430935, 2019). "Furthermore, CHIP assay confirmed that Stat3 did not bind to the IDO promoter region GAS in lung cancer cells in forced Jak3–Leu905 expressed cells." (PMID 32038231, 2019). "Furthermore, another approach to identify lung cancer-treated ADSCs is detecting the secretion of IL-6 family cytokines, including IL-6, IL-11 and LIF, as initiators of the cytokine cascade that leads to STAT3 activation." (PMID 31196220, 2019). "Interestingly, deletion of STAT3, but not RelA, increased MHC-I expression in lung cancer cells, indicating a specific role for STAT3." (PMID 31757943, 2019). "The present study revealed that BBI608 could eradicate EGFR-positive lung cancers and demonstrated that STAT3 enhanced the expression of HER3 through miR-145-5p repression by G9a, indicating that STAT3 is a reliable therapeutic target against EGFR-TKI-resistant lung cancers." (PMID 31619200, 2019). "Furthermore, we also found that the knockdown of KLF3 increased the luciferase activity of the STAT3 gene promoter but not the luciferase activity of the mutant promoter in lung cancer cells." (PMID 31486564, 2019). "For this reason, combinative inhibition of EGFR and IL‐6/STAT3 pathway rather than blockade of EGFR alone might therefore be more effective in the treatment of lung cancer." (PMID 31507089, 2019). "Considering the crucial role of STAT3 in tumor progression and the contribution of KLF3 to the effects of STAT3, we examined whether STAT3 is essential for metastasis‐mediated knockdown of KLF3 in lung cancer cells." (PMID 31486564, 2019). "Moreover, resveratrol displayed a dose-dependent and time-dependent cytotoxicity on lung cancer cells A549 through inhibiting the mRNA and protein expression of STAT-3, while overexpression of STAT-3 completely or partially blocked the effects of resveratrol on A549 cells." (PMID 30584449, 2018). "We have recently shown that gefitinib or osimertinib treatment results in the activation of not only STAT3, but also Src-YAP1 signaling, potentially operating downstream of IL-6, to promote cell survival and limit the initial response to EGFR TKI treatment in EGFR mutant lung cancer." (PMID 28521301, 2017).
lung carcinoma (continued). "Collectively, we show that TM4SF4 in lung cancer cells mediates the activation of a positive feedback autocrine loop between OPN and STAT3 pathways, resulting in cancer stemness and radiation resistance, and suggest targeting TM4SF4 or OPN may be useful as a cancer treatment." (PMID 29254164, 2017). "The STAT3-induced downregulation of MDR1 and MRP1 might increase the intercellular concentration of paclitaxel and subsequently trigger apoptosis in paclitaxel resistant lung cancer cells." (PMID 29072615, 2017). "To verify if STAT3 also plays a role in human tumor cell growth regulated by HDAC7, we tested whether expression of dnStat3 was able to rescue the growth suppression mediated by HDAC7 depletion in human lung cancer cell lines." (PMID 29126425, 2017). "Thus, BDNF-regulated STAT3 activation can further strengthen BDNF expression, which may be the reason for enhanced STAT3 and TrkB activation in lung cancer." (PMID 27456333, 2016). "Indeed, a previous report showed that suppression of EGFR signaling induced Stat3 activation in EGFR-mutant but not in EGFR wildtype lung cancer cells." (PMID 27419630, 2016). "After 6 h with HHT treatment, IL-6-induced STAT3 phosphorylation in A549 and H1975 cells almost recovered which indicated that the HHT inhibition on STAT3 phosphorylation in lung cancer was reversible and the recovery was not due to new synthesized STAT3 protein by CHX-treatment experiment." (PMID 26166037, 2015). "Interestingly, the inhibition of STAT1 activation led to increased STAT3 activation in IL-27 treated lung cancer cells whereas inhibition of STAT3 activation alone did not significantly impact STAT1 expression." (PMID 24274066, 2013). "We also attempted to assess the correlation between miR-337-3p expression levels, taxane response and levels of STAT3 and pSTAT3, but miR-337-3p was not detectable in most of the lung cancer cell lines, and therefore not amenable to such an analysis (data not shown)." (PMID 22723956, 2012). "STAT3 decoy ODN significantly suppressed lung cancer cells in vitro and in vivo, indicating that STAT3 decoy ODN may be a potential therapeutic approach for treatment of lung cancer." (PMID 17683579, 2007). "In addition, we have provided strong evidence that the JAK2/STAT3/C/EBPβ-induced IL-6 positive feedback pathway is important for lung cancer cell growth, migration, and invasion, which suggests that the STAT3-C/EBPβ-IL-6 signaling axis plays a crucial role in TAM-mediated lung cancer progression." (PMID 38424624, 2024). "Therefore, non-oncology drugs capable of targeting STAT3 may have therapeutic potential in lung cancer." (PMID 36559280, 2022). "Although the possibility that the Pdia4/Stat3/Vegf axis also functions in cancer cells could not be excluded, both lines of evidence suggest that targeting Pdia4 in the cancer stroma and cancer cells is a promising two‐pronged approach to treating lung cancer." (PMID 35170261, 2022). "To understand the biological functions of STAT3 in lung cancer and to determine whether noncanonical function of STAT3 plays a role in lung cancer development, we investigated the interaction between STAT3 and HP1α in a few non-small cell lung cancer (NSCLC) cell lines." (PMID 32087696, 2020). "Signal transducer and activator of transcription 3 (STAT3), a vital prooncogenic transcription factor in multiple cancers, is constitutively activated in approximately 50% of NSCLC primary tumors and lung cancer-derived cell lines and may be one of the most important oncogenic drivers in NSCLC." (PMID 30838170, 2019). "To further elucidate whether ATM downregulates PD-L1 via JAK1,2/STAT3 pathway, we generated ATM-overexpression A549CisR and H157CisR cells (A549CisR-ATM and H157CisR-ATM) and confirmed that ATM-overexpression increased the expression of PD-L1 expression in lung cancer cells." (PMID 30961670, 2019). "However, the role of STAT3 in lung cancer tumorigenesis and therapy has not been fully addressed." (PMID 22723956, 2012).